GMCL2 (germ cell-less 2, spermatogenesis associated)
Description:
Possible function in spermatogenesis. Probable substrate-specific adapter of an E3 ubiquitin-protein ligase complex which mediates the ubiquitination and subsequent proteasomal degradation of target proteins.
Synonyms: GCL; GMCL1L; GMCL1P1
Tractability: PROTAC: ubiquitination databases record sites on it.
Gene: Protein-coding gene on chromosome 5 (178,184,505 to 178,187,371, reverse strand). Ensembl gene ENSG00000244234.
Subcellular location: Nucleus matrix
Gene Ontology:
Molecular function: cullin family protein binding; protein binding
Biological process: germ cell development; protein ubiquitination
Cellular component: nucleus; nuclear matrix
Genetic constraint (gnomAD): Loss-of-function variants: 6 observed, 9.84 expected, observed/expected ratio (o/e) 0.61, 90% interval 0.33 to 1.2. That is too few expected variants to judge how well the gene tolerates losing a copy. Missense variants: 83 observed, 110.47 expected, observed/expected ratio (o/e) 0.75, 90% interval 0.63 to 0.9. Synonymous variants: 31 observed, 38.42 expected, observed/expected ratio (o/e) 0.81, 90% interval 0.61 to 1.09.
Homologues: Orthologues: macaque GMCL2 (91% identical), dog GMCL1 (87% identical), rat Gmcl1 (85% identical), mouse Gmcl1 (85% identical), tropical clawed frog gmcl1 (71% identical), zebrafish gmcl1 (66% identical), Drosophila melanogaster gcl (33% identical), Caenorhabditis elegans gcl-1 (25% identical). Paralogues in human: GMCL1 (89% identical), BTBD16 (19% identical), C10orf120 (10% identical).